ROR2 (ROR family WNT receptor 2)
Diseases named in the same sentence as ROR2 in open-access papers (continued):
Sharing a sentence is not in itself a finding about the gene and the disease.
ovarian carcinoma (17 papers, 2015 to 2023). A malignant neoplasm originating from the surface ovarian epithelium. "We are now investigating ROR2 expression in other ovarian cancer cohorts to see if this survival association holds true." (PMID 26515598, 2015). "This trend is opposite to that reported of ROR1 in ovarian cancer, and ROR2 in other tumours, where ROR2 expression has been associated with worse overall or disease specific survival." (PMID 26515598, 2015). "Knowing that the blockage of ROR2 expression by using an anti-human antibody caused an 80% decrease in the migration of Wnt5A-transfected cells, it may be suspected that in the case of ovarian cancer, bacterial cell wall fragments may have anti-metastatic potential." (PMID 37608943, 2023). "In ovarian cancer ROR1 was described to have a synergistic effect with ROR2 on cell proliferation, since only a double knockdown led to a significant reduction in tumor cell proliferation." (PMID 33445713, 2021). "In contrast, in a study on ovarian cancer the induction of ROR2 expression in the tumor cells led to endoplasmic reticulum stress and decreased cell viability." (PMID 33445713, 2021). "In contrast, other studies showed that ROR2 inhibited proliferation in gastric, colorectal, and ovarian cancer, as well as in esophageal squamous cell carcinoma." (PMID 34774050, 2021). "While ROR2 was found upregulated in a large ovarian carcinoma cohort compared with normal ovarian tissue, another report investigating aggressive high-grade serous ovarian carcinoma has claimed the opposite." (PMID 33445713, 2021). "In gynaecological cancers, ROR2 has been shown to be upregulated in ovarian cancer patients compared to benign cases, and high ROR2 expression was significantly correlated with poor prognosis in cervical cancer." (PMID 33494187, 2021). "To further verify the effects of ROR2 on the proliferation assay of ovarian cancer cells, we used HO-8910 cells to construct stable overexpression cell model with Lentivirus PCMV-NC or PCMV-ROR2." (PMID 31878941, 2019). "More recently, a study by Caroline Ford’s group used this model to expand on the synergistic role of Wnt receptors ROR1 and ROR2 in early ovarian cancer metastasis, specifically their role in ovarian cancer cell adhesion to the omentum." (PMID 30096959, 2018). "We previously demonstrated that silencing both ROR1 and ROR2 simultaneously significantly inhibited the ability of ovarian cancer cells to proliferate, migrate and invade in vitro." (PMID 29348860, 2017). "The expression of ROR2 was increased in the chemoresistant ovarian cancer and mediate cell migration and invasion via EMT." (PMID 29108281, 2017). "Elevated expression of the ROR1 and ROR2 Wnt receptors has been noted in both the tumour and stromal compartments of ovarian cancer patient tissue samples." (PMID 29348860, 2017). "We have confirmed previous findings that ROR1 and ROR2 have a synergistic role in ovarian cancer invasion, and have presented new evidence that they are also important in adherence to omentum, the critical first step in ovarian cancer metastasis." (PMID 29348860, 2017). "Here we report that ROR1 and ROR2 expression is increased in this chemoresistant cell line and support our initial findings that ROR1 and ROR2 regulate ovarian cancer cell migration and invasion." (PMID 27239958, 2016). "ROR1 and ROR2 are upregulated in a chemoresistant model of ovarian cancer and regulate cell migration and invasion through EMT." (PMID 27239958, 2016). "Here we investigated the role of two Wnt receptor tyrosine kinases (RTKs), ROR1 and ROR2, and their putative ligand, Wnt5a, in ovarian cancer." (PMID 26515598, 2015). "Here, we have shown that the receptor for the Wnt5a ligand, ROR2, is also increased in epithelial ovarian cancer patients." (PMID 26515598, 2015).
ovarian carcinoma (continued). "ROR2 expression is increased in epithelial ovarian cancer, and silencing ROR2 and its sister receptor ROR1 has a strong inhibitory effect on the ability of ovarian cancer cells to proliferate, migrate and invade through an extracellular matrix." (PMID 26515598, 2015). "It will be important to elucidate the mode in which ROR1 and ROR2 signal in epithelial ovarian cancer." (PMID 26515598, 2015). "We have shown for the first time that both ROR1 and ROR2 regulate ovarian cancer cell migration and invasion." (PMID 26515598, 2015). "Immunohistochemistry for ROR2 was performed in a large patient cohort, including benign controls, borderline tumours and epithelial ovarian cancer." (PMID 26515598, 2015). "Tissue sections from ovarian cancer patients had a significantly higher expression of ROR2 than tissue sections taken from benign controls (p = 0.0017)." (PMID 26515598, 2015). "ROR2 expression is significantly increased in ovarian cancer patients compared to patients with benign disease." (PMID 26515598, 2015). "Contradictory findings for ROR2 have been reported for endometrial, colorectal, and ovarian cancer." (PMID 33445713, 2021). "Different to the oncogenic role of the two receptors in ovarian cancer where both receptors are overexpressed and associated with survival, our previous study in EC suggested distinct roles for ROR1 and ROR2, with high ROR1 and low ROR2 expression associated with shorter survival." (PMID 33494187, 2021). "ROR2 expression is significantly increased in ovarian cancer." (PMID 31673248, 2019). "However, Ror1 over expression in the parental cell line increased cell invasion, indicating that Ror1 and Ror2 have potential as novel drug targets in metastatic and recurrent ovarian cancer patients." (PMID 28432357, 2017). "The combination of ROR1 and ROR2 signalling influences ovarian cancer dissemination to the omentum, however ROR2 may also play a role in stromal activation during metastasis." (PMID 29348860, 2017). "In this study, we aimed to understand whether inflammatory mediators such as lipopolysaccharide (LPS), lipoteichoic acid (LTA) or recombinant human IL-6 (rhIL-6) can modulate Wnt5A and ROR2 expression in the human ovarian cancer cell line SKOV-3." (PMID 28536612, 2016). "Therefore, ROR1 and ROR2 have the potential as novel drug targets in metastatic and recurrent ovarian cancer patients." (PMID 27239958, 2016). "ROR1 and ROR2 present as possible targets for novel therapies for the treatment of ovarian cancer." (PMID 27239958, 2016). "In addition, siRNA was used to silence ROR1, ROR2 and Wnt5a individually, and together, in two ovarian cancer cell lines, and the effects on cell proliferation, adhesion, migration and invasion were measured." (PMID 26515598, 2015). "Based on our previous results supporting the upregulation of β-catenin independent Wnt signalling in ovarian cancer, we hypothesised that ROR2 would also be upregulated in ovarian cancer patients." (PMID 26515598, 2015). "Moreover for the first time our study also includes ROR2, and shows that it is also overexpressed in ovarian cancer, and may play a role in cancer progression." (PMID 26515598, 2015). "Therefore this difference may be due to the multiple confounders that cannot be controlled for in long-term survival data, or may highlight a different function for ROR2 in ovarian cancer." (PMID 26515598, 2015). "In ovarian cancer, stroma cell expression of ROR1 was lower than in the tumor cells, while the opposite was true for ROR2." (PMID 33445713, 2021). "In ovarian cancer, a comparative analysis has revealed that ROR1 was largely expressed in cancer cells, while the number of patients with ROR2-positive tumors was significantly lower." (PMID 33445713, 2021). "Therefore, targeting both ROR1 and ROR2 may be a powerful approach to treating ovarian cancer." (PMID 29348860, 2017).
ovarian carcinoma (continued). "We recently demonstrated that ROR2 and its sister receptor, ROR1, regulate ovarian cancer migration and invasion." (PMID 27239958, 2016). "This study revealed for the first time that inflammatory mediators modulate Wnt5A and ROR2 through NF-kB and STAT3 transcription factors and this may play a role in ovarian cancer cell migration." (PMID 28536612, 2016). "Although most of such data derive from in vitro models using cancer cell lines, in vivo experimental data supporting oncogenic roles for ROR2 have been reported in melanoma, renal cell carcinoma, ovarian cancer, and breast cancer, as well as for RYK in gastric and ovarian cancer." (PMID 34716856, 2022). "In addition, we also sought to determine the therapeutic potential of targeting these receptors by performing an extensive suite of in vitro experiments, exploring the functional role of ROR2, its sister receptor, ROR1 and putative ligand, Wnt5a in ovarian cancer." (PMID 26515598, 2015). "Thus, the combination of our results here in ovarian cancer and recent others, suggests that in gynaecological cancers both ROR1 and ROR2 may be over expressed, and important for disease progression." (PMID 26515598, 2015). "Our findings here are further supported by the fact that Knockdown of either ROR1 or ROR2 alone did not affect cell adhesion to collagen or fibronectin, suggesting that the ROR receptors do not play a major role in regulating ovarian cancer cell adhesion." (PMID 33723319, 2021).
colon cancer (16 papers, 2010 to 2024). "Here we report that ROR2 is frequently repressed by promoter hypermethylation in colon cancer and that its loss can be protumourigenic in colon cancer." (PMID 20591152, 2010). "The data indicate that ROR2 promoter hypermethylation is directly associated with ROR2 repression in colon cancer, both in vitro and in vivo." (PMID 20591152, 2010). "In cancers where canonical Wnt signalling is a key driver of the disease (eg through mutations in β-catenin or APC), such as colon cancer, ROR2 may play a major role in inhibiting the canonical pathway through binding to Wnt5a." (PMID 32807831, 2020). "In addition, we demonstrate that the epigenetic-dependent loss of ROR2 can promote tumour growth in colon cancer cells." (PMID 20591152, 2010). "Noteworthy, disease suppressive relationships of ROR2 have been described in hepatocellular cancer, colon cancer, and hematological malignancies." (PMID 31798639, 2019). "Restoration of ROR2 expression reduced basal β-catenin/TCF-dependent transcription in DLD1 cells by 50%, suggesting that the role of aberrant epigenetic repression of ROR2 in colon cancer is mediated, at least in part, by canonical Wnt signalling." (PMID 20591152, 2010). "We also knocked down ROR2 expression by RNA interference in a ROR2-expressing colon cancer cell line unmethylated at the ROR2 CpG island, SW480." (PMID 20591152, 2010). "Our data show the importance of epigenetic alterations of ROR2 in colon cancer, highlighting the close interconnection between canonical and non-canonical Wnt signalling pathways in this type of tumour." (PMID 20591152, 2010). "We used colony-formation assays to further characterise the role of ROR2 in the growth of colon cancer cells, and found that restoration of ROR2 activity resulted in a 30% reduction in colony formation in DLD1 cells." (PMID 20591152, 2010). "By restoring ROR2 activity in colon cancer cells harbouring ROR2 promoter hypermethylation, we show that the role of ROR2 in colon cancer cells is mediated, at least in part, by canonical Wnt and that its epigenetic-dependent loss can be pro-tumourigenic." (PMID 20591152, 2010). "To study the relationship between ROR2 promoter hypermethylation and ROR2 repression in more detail, we analysed ROR2 mRNA levels in colon cancer cell lines incubated with the demethylating drug 5-aza-2-deoxycytidine." (PMID 20591152, 2010). "Similarly, WNT5A regulates cellular migration and invasion in various types of colon cancers with a dependency on ROR2 function." (PMID 37722040, 2023). "As ROR2 shows a similar role in EC as in colon cancer, the epigenetic repression of ROR2 could be a possible explanation for the abnormal nuclear accumulation of β-catenin in subtypes of EC lacking β-catenin mutations." (PMID 33494187, 2021). "However, a previous study in colon cancer showed that restoration of the tumour suppressor ROR2 impaired tumour growth through inhibition of β-catenin-dependent Wnt signalling, in a Wnt5a independent manner." (PMID 33494187, 2021). "In addition to its function as an oncogene, and in contrast to ROR1, ROR2 can also act as a suppressor of carcinogenesis in tumors driven by canonical Wnt signaling, where ROR2 expression is lost, as observed in colon cancer and hepatocellular carcinoma." (PMID 30450096, 2018). "Since we found that Wnt5b is important for proliferation of HCT116 colon cancer cells in β-catenin-independent manner we decided to test whether RoR2 is important for proliferation of these cells as well." (PMID 29453334, 2018). "As ROR2 is reported to mediate the WNT5A-dependent inhibition of β-catenin-TCF-regulated genes in human embryonic cells, we tested whether WNT5A mediated the canonical Wnt-dependent role of aberrant epigenetic ROR2 repression in colon cancer." (PMID 20591152, 2010).
colon cancer (continued). "At the mRNA level, in 18 of the 20 paired samples analysed, ROR2 was much less strongly expressed in tumour tissues than in their normal counterparts; mean ROR2 expression was seven times higher in colon epithelium than in colon tumours." (PMID 20591152, 2010). "This in vivo evidence links ROR2 aberrant promoter hypermethylation with colon cancer development." (PMID 20591152, 2010). "However, it has been shown that epigenetic silencing of Ror2 in colon cancer promotes cell proliferation and tumor growth, suggesting that depending on the cellular context Ror2 could also act as a tumor-suppressor." (PMID 26680417, 2015). "We thus hypothesised that the role of ROR2 in colon cancer is mediated by canonical Wnt signalling." (PMID 20591152, 2010). "We report that the receptor tyrosine kinase-like orphan receptor 2 (ROR2), a transmembrane protein that participates in Wnt signalling, is frequently repressed by aberrant promoter hypermethylation in human colon cancer." (PMID 20591152, 2010). "To evaluate the functional role of ROR2 repression by promoter hypermethylation in colon cancer, we transfected ROR2 in the colon cancer cell line DLD1, which shows DNA methylation-dependent ROR2 inactivation." (PMID 20591152, 2010). "Furthermore, Wnt5A and its receptor, ROR2, were found to upregulate AKT/PKB survival signaling in histone deacetylase inhibitor-resistant colon cancer." (PMID 25401518, 2014). "Our data thus suggest that the canonical Wnt-dependent role of ROR2 hypermethylation in colon cancer cells does not necessarily require WNT5A." (PMID 20591152, 2010). "As WNT5A might have canonical and non-canonical effects, WNT5A/ROR2 could have a role in colon cancer through non-canonical Wnt signalling within certain molecular contexts." (PMID 20591152, 2010). "Increasing or decreasing extracellular WNT5A levels had little impact on β-catenin nuclear location and β-catenin/TCF-dependent transcription, suggesting that the canonical Wnt-dependent role of ROR2 epigenetic deregulation in DLD1 colon cancer cells does not necessarily require WNT5A." (PMID 20591152, 2010). "As ROR2 mediates the inhibition of canonical signalling by WNT5, we hypothesised that this orphan receptor could also be a target of aberrant epigenetic regulation in colon cancer." (PMID 20591152, 2010). "Here we report that the receptor tyrosine kinase-like orphan receptor 2 (ROR2), a transmembrane receptor for Wnt factors that activates non-canonical pathways, is frequently repressed by aberrant promoter hypermethylation in human colon cancer cell lines and primary tumours." (PMID 20591152, 2010). "Indeed, the ROR2 extracellular ligand WNT5A, which inhibits the canonical Wnt signalling pathway in certain molecular contexts, is also aberrantly repressed by promoter hypermethylation in acute lymphoblastic leukaemia and in colon cancer, and its absence is tumourigenic in these tumour types." (PMID 20591152, 2010). "Additional studies with the human colon cancer cells SW620, and the derived from them SW620R cells, that grow at 3 mM butyrate, indicated that these cells do not express detectable levels of ROR2 (data not shown); however, they express WNT5A, and exposure to butyrate increases pAKT levels." (PMID 22073312, 2011).
prostate carcinoma (14 papers, 2014 to 2025). A carcinoma that arises from epithelial cells of the prostate gland. "In contrast, downregulation of ROR2 in solid tumor cells, compared with adjacent normal tissue, has been described for gastric and prostate carcinoma." (PMID 33445713, 2021). "Variation in Ror2 expression level altered the sensitivity of prostate cancer cells to both drugs identifying a possible new target for taxane resistance." (PMID 32484838, 2020). "Because of its critical role in different cancer entities, we expected a striking effect of ROR2 in prostate cancer." (PMID 29930766, 2018). "To assess if this was limited to our in vitro studies, we analyzed ROR2 mRNA expression in a prostate cancer cDNA array." (PMID 29930766, 2018). "FZD7, FZD8, and ROR2 showed the lowest expression in most of the prostate cancer cell lines, while FZD6 and RYK were abundantly expressed." (PMID 29930766, 2018). "Genes previously implicated in prostate cancer (PAK4, TNK2) and genital dysplasia (ROR2) also demonstrated mutations." (PMID 28423512, 2017). "Knockdown of ROR2 by shRNA blocked the suppressive effects of CAPE on prostate cancer cell migration." (PMID 27191743, 2016). "Further, observations of the aberrant expression of Ror2 in prostate cancer and RCC cells have shown alterations in MMP1 and MMP2 expression, respectively." (PMID 25542006, 2014). "Protein Wnt-5a (Wnt5a) expression in the osteoblastic niche has been found to promote dormancy in a model of prostate cancer via the activation of the Wnt5a/tyrosine-protein kinase transmembrane receptor ROR2 (ROR2)/E3 ubiquitin-protein ligase SIAH2 (SIAH2) signalling axis." (PMID 36701089, 2023). "Moreover, WNT5A secreted by the osteoblastic niche was observed to induce dormancy in prostate cancer cells via ROR2 by repressing canonical WNT signaling and thus inhibiting bone metastasis." (PMID 33445713, 2021). "Furthermore prostate cancer invasion has been described to depend on ROR2 and FZD2." (PMID 29930766, 2018). "Besides, this mechanism of dormancy induction was showed to depend on ROR2, whose expression was inversely correlated with the disease-free survival (DFS) rates in prostate cancer patients who developed bone metastasis." (PMID 36701089, 2023). "CAPE treatment of prostate cancer cells induced ROR2 (receptor tyrosine kinase-like orphan receptor 2) and Wnt5a expression, which are involved in the non-canonical Wnt signaling pathway." (PMID 34444754, 2021). "In this study, a negative correlation between ROR2 expression and metastasis-free survival in patients with prostate cancer was observed, potentially offering new potential therapeutic opportunities." (PMID 33193295, 2020). "However, Wnt5a has also been reported to play an opposing tumor-suppressive role by abrogating the YAP/TAZ pathway, as evidenced by its negative feedback in the ROR2-YAP/TAZ pathway in a prostate cancer model." (PMID 40542295, 2025). "However, ROR2 was barely expressed in prostate cancer cell lines and hence, also the knock-down did not influence proliferation and apoptosis." (PMID 29930766, 2018). "Similarly, ROR2 was not differentially expressed in healthy and primary prostate cancer tissue and did not correlate with WNT5A expression." (PMID 29930766, 2018). "Therefore, ROR2 may not mediate the anti-tumor effects of WNT5A in primary prostate cancer, but may have a more significant role in metastasized prostate cancer stages." (PMID 29930766, 2018).